CDH13 (cadherin 13)
Diseases named in the same sentence as CDH13 in open-access papers (continued):
Sharing a sentence is not in itself a finding about the gene and the disease.
neurodevelopmental disorder (7 papers, 2013 to 2024). A behavioral and cognitive disorder with onset during the developmental period that involves impaired or aberrant development of intellectual, motor, or social functions. "CDH13 deficiency results in behavioral alterations associated with symptoms observed in neurodevelopmental disorders such as ADHD, including learning and memory deficits as well as locomotor hyperactivity." (PMID 26460479, 2015). "We recently demonstrated that CDH13 contributes to the migration of 5-HT specific neurons to distinct subregions of the raphe nuclei, preferentially the lateral wing of the dorsal raphe and has been associated with various neurodevelopmental disorders including ADHD and ASD." (PMID 33560471, 2021). "Additionally, the consequence of CDH13 deficiency on brain 5-HT system development was investigated in a Cdh13 knockout mouse, a model for loss-of function mutations at the CDH13 locus presumed to cause neurodevelopmental disorders." (PMID 29018333, 2017). "Due to the importance of CDH13 for neurodevelopmental disorders, the expression of this protein was analyzed in hiPSC-derived 5-HT specific neurons using epifluorescence microscopy and SIM." (PMID 33560471, 2021). "In summary, CDH13 deficiency impacts locomotor activity as well as learning and memory, two behavioral domains frequently associated with ADHD and related neurodevelopmental disorders." (PMID 26460479, 2015). "Our findings of altered 5-HT system development in Cdh13-deficient mice resulting in serotonergic hyperinnervation of the cortex is in line with the notion of a CDH13-driven pathogenetic mechanism affecting brain 5-HT system function in neurodevelopmental disorders." (PMID 29018333, 2017). "Moreover, the pattern of brain expression of CDH13 and its presumed role in migratory processes of the developing brain, makes this a strong candidate for neurodevelopmental disorders." (PMID 23936508, 2013). "Therefore, future studies that focus on CDH13 in neurodevelopmental disorders should concentrate on the role of CDH13-mediated neuronal outgrowth in attentional networks, such as frontostriatal circuits and hippocampal regions, in both rodent models and human studies." (PMID 34573337, 2021). "The impact of CDH13 dysfunction on formation of the 5-HT system specifically and brain function in general may be relevant for the etiopathogenesis of neurodevelopmental disorders." (PMID 29018333, 2017). "In the nervous system, CDH13 togetherwith PCDH19 is found in synaptic space controlling vital neuronal processesincluding axonal outgrowth and synaptic formation, consistent with their geneticcontribution to a number of neurodevelopmental disorders." (PMID 38629124, 2024).
adenocarcinoma (5 papers, 2007 to 2020). A common cancer characterized by the presence of malignant glandular cells. "Their results showed two hypomethylated genes (CDKN2A and MGMT) and three hypermethylated genes (CDH13, RUNX3, APC) in adenocarcinomas compared with SCC, with the higher sensitivity and specificity values of CDH13 and APC." (PMID 32604993, 2020). "Five remaining loci, CDH13, CDX2, OPCML, SFRP1 and TWIST1 were designated as “late” loci; significantly elevated DNA hypermethylation was only detected in adenocarcinoma, as compared with AIS." (PMID 21731750, 2011).
metabolic disorders (5 papers, 2014 to 2025). "Several studies have established a link between the gene that encodes T-cadherin, cadherin 13, and various metabolic diseases." (PMID 30150999, 2018). "For instance, the variants in the CDH13 gene, involved in metabolic disorders, might be this case." (PMID 38321133, 2024). "Interestingly CDH13 abundance differs according to metabolic disorders and is decreased in obese mouse models." (PMID 41164751, 2025).
colorectal (4 papers, 2017 to 2025). "By contrast, there are many reports which indicate insufficient T-cadherin (also known as CDH13 and H-cadherin) expression, the third receptor of adiponectin, in colorectal carcinogenesis." (PMID 28422056, 2017).
infection (4 papers, 2015 to 2022). The state of being infected such as from the introduction of a foreign agent such as serum, vaccine, antigenic substance or organism. "CDH13 genotype and expression have also been linked to an increased risk of Campylobacter jejuni infection, and the Campylobacter phylum had a 4-fold increased abundance in the feces of Mal animals, indicating an increased risk of infection." (PMID 36118759, 2022). "Western blot analysis confirmed a roughly 85% efficiency in CDH13 silencing in ECs compared to control levels at 96 h post‐infection." (PMID 35439361, 2022).
psychiatric disorder (4 papers, 2015 to 2021). A disorder characterized by behavioral and/or psychological abnormalities, often accompanied by physical symptoms. "CDH13 involvement in neuropsychiatric disorders is well documented, associated with the five major psychiatric disorders: ADHD, ASD, MDD, BD, and SCZ." (PMID 33897758, 2021). "CDH13 variation has been associated with neurodevelopmental and psychiatric disorders in numerous linkage, copy-number variant (CNVs), genome-wide association (GWAS), and whole-exome sequencing (WES) studies." (PMID 29018333, 2017). "Here, we focused on the hippocampus to test in vivo the hypothesis that involvement of CDH13 in the susceptibility to neurodevelopmental/psychiatric disorders is associated with its potential role in the modulation of synaptic function." (PMID 26460479, 2015).
CDH13 also shares sentences with these, for which no sentence is quoted: alcohol dependence (5 papers); cardiac hypertrophy (4); leukemia (4); bipolar disorder (3); chronic myeloid leukemia (3); cutaneous squamous cell carcinoma (3); heart failure (3); acute coronary syndrome (2); acute myeloid leukemia (2); amyotrophic lateral sclerosis (2); asthma (2); coronary atherosclerosis (2); Hyperglycemia (2); mastitis (2); migraine (2); nasopharyngeal carcinoma (2); pituitary adenomas (2); thyroid cancer (2); acute kidney injury (1); adrenocortical carcinoma (1); Alagille syndrome (1); alcoholism (1); ampullary carcinoma (1); Aphasia (1); arrhythmogenic right ventricular cardiomyopathy (1); Atherosclerotic lesion (1); autoimmune disease (1); Autoimmunity (1); bronchioloalveolar carcinoma (1); carcinoma in situ (1).
A further 62 diseases each share a sentence with CDH13 in 1 paper.